APLN (apelin)
Diseases named in the same sentence as APLN in open-access papers (continued):
Sharing a sentence is not in itself a finding about the gene and the disease.
colon adenocarcinoma (6 papers, 2016 to 2023). "To validate this in another species, we tested apelin expression in mice suffering from cachexia because of one of these tumors: colon adenocarcinoma (C26), methylcholanthrene-induced sarcoma (MCG101), or Lewis Lung carcinoma (LLC)." (PMID 35406586, 2022). "However, co-expression of apelin and APJ was observed in malignant lesions in both human and mouse models, suggesting that apelin signaling could act on pancreatic tumor cells through an autocrine/paracrine loop, as demonstrated in colon adenocarcinoma." (PMID 36142542, 2022). "Co-expression of Apelin and APJ in tumor is the basis of an autocrine loop involved in the growth of colon adenocarcinomas." (PMID 27733135, 2016). "D-apelin 13 given intraperitoneally for 13 days in colon adenocarcinoma C26-bearing mice does not reduce catabolic pathways in muscles, as it does in vitro." (PMID 35406586, 2022).
esophageal cancer (6 papers, 2021 to 2025). A primary or metastatic malignant neoplasm involving the esophagus. "Previous studies showed that knocking down apelin significantly suppressed cell proliferation and migration and promoted cell apoptosis in esophageal cancer cells in vitro, potentially by activating PI3K/mTOR signaling pathway." (PMID 37968758, 2023). "KEGG enrichment analysis showed that prenylation-related proteins detected in esophageal cancer were mainly engaged in the RAS signaling pathway, serotonin synapse, regulation of autophagy, chemokine signaling pathway, and apelin signaling pathway." (PMID 37328063, 2023). "constructed a prognostic map for esophageal cancer, utilizing eight genes, including CDCA4, UBE2Z, AMTN, AK1, TLE1, FXN, ZBTB6, and APLN." (PMID 38098487, 2023).
hypertrophic cardiomyopathy (6 papers, 2021 to 2024). A condition in which the myocardium is hypertrophied without an obvious cause. "Multiple linear regression analysis for the association between plasma apelin levels and clinical characteristics in patients with obstructive hypertrophic cardiomyopathy." (PMID 35783816, 2022). "Correlation between clinical characteristics and plasma apelin levels of patients with obstructive hypertrophic cardiomyopathy." (PMID 35783816, 2022). "Characteristics of patients with obstructive hypertrophic cardiomyopathy according to plasma apelin levels stratified by mean value." (PMID 35783816, 2022). "However, there are few data concerning apelin levels in patients with obstructive hypertrophic cardiomyopathy (OHCM) or the relationship between apelin levels and severity of OHCM." (PMID 35783816, 2022).
kidney damage (6 papers, 2018 to 2025). "Elevated apelin has been implicated in impairing podocyte function, increasing glomerular endothelial permeability, and promoting abnormal angiogenesis, which may exacerbate kidney damage." (PMID 39857634, 2024). "In diabetic mice with nephropathy, apelin promotes podocyte apoptosis, which appears to be inversely related to podocyte autophagy." (PMID 39857634, 2024). "In diabetes-related diseases, such as retinopathy, nephropathy or cardiomyopathy apelin has a protective effect against oxidative stress and apoptosis through the mTOR pathway." (PMID 29875677, 2018). "Apelin was also responsible for podocyte apoptosis, which was negatively correlated with podocyte autophagy in diabetic mice with nephropathy." (PMID 29875677, 2018). "In conclusion, apelin may be a potentially curative candidate for prohibiting kidney damage and have a therapeutic benefit in PE rat models." (PMID 33850656, 2021). "Moreover, apelin ameliorated kidney damage in a PE rat model; hence, it might represent a curative candidate for prohibiting kidney damage." (PMID 35011661, 2021). "For example, while apelin and VEGF exhibit renoprotective effects in some cases, their dysregulation can worsen kidney damage, complicating efforts to design targeted interventions." (PMID 39857634, 2024).
rheumatoid arthritis (6 papers, 2012 to 2025). A chronic, systemic autoimmune disorder characterized by inflammation in the synovial membranes and articular surfaces. "This study aimed to assess the role of chemerin, apelin, vaspin, and omentin adipokines and their genetic variants rs17173608, rs2235306, rs2236242, and rs2274907, respectively, in rheumatoid arthritis (RA) pathogenesis in Egyptian patients." (PMID 34683117, 2021). "APLN has a crucial role in the pathogenesis of arthritic diseases, including rheumatoid arthritis and OA." (PMID 32420902, 2020).
alcoholism (5 papers, 2020 to 2025). "KEGG pathway enrichment analysis showed that DNA replication, Apelin signaling pathway, Glucagon signaling pathway, cGMP-PKG signaling pathway, PI3K-Akt signaling pathway, AMPK signaling pathway, Alcoholism, and Cocaine addiction might be involved in the pathological process of EMs and RPL." (PMID 35601407, 2022).
cholangiocarcinoma (5 papers, 2019 to 2025). A carcinoma that arises from the intrahepatic biliary tree (intrahepatic cholangiocarcinoma) or from the junction, or adjacent to the junction, of the right and left hepatic ducts (hilar cholangiocarcinoma). "In patients with cholangiocarcinoma, APLN and APLNR genes were obviously upregulated in tumor tissues compare to nonmalignant liver tissues." (PMID 36193059, 2022). "In cholangiocarcinoma, expression of the apelin/APJ was increased." (PMID 33912466, 2021). "In vitro, apelin could promote human cholangiocarcinoma cells Mz-ChA-1 proliferation and angiogenesis which could be inhibited by ML221." (PMID 33912466, 2021). "The authors suggested, that tumor environment could promote upregulation of apelin and APJ in cholangiocarcinoma." (PMID 31547096, 2019).
epilepsy (5 papers, 2019 to 2022). A brain disorder characterized by episodes of abnormally increased neuronal discharge resulting in transient episodes of sensory or motor neurological dysfunction, or psychic dysfunction. "Apelin can exert a level of neuroprotection in the PTZ model of epilepsy thanks to its ability to maintain mitochondrial potentials, reduce intracellular Ca2+, and inhibit ROS generation and COX2 (Cyclooxygenase 2)." (PMID 36421846, 2022). "Treatment with brain-specific micro-RNA-182 (miR-182) that blocks Apelin leads to increased apoptosis in epilepsy models." (PMID 36421846, 2022). "Further research on the efficiency of apelin showed that the neuroprotective mechanism of action includes suppressing apoptosis of hippocampal neurons by down-regulation of Bax and caspase-3 expression in both in vitro and in vivo epilepsy models." (PMID 36611944, 2022). "Increasing the expression of miR-182 may weaken the protective effect of apelin on neuronal damage in the rat epilepsy model." (PMID 36611944, 2022). "The observed overexpression of Apelin in patients with drug-resistant temporal lobe epilepsy and rats with lithium–pilocarpine-induced epilepsy may be a compensatory mechanism." (PMID 36421846, 2022). "Central apelin has a regulatory effect on memory and epilepsy, and it could protective memory impairment in rodents." (PMID 32231577, 2020).
Glucose intolerance (5 papers, 2016 to 2022). Glucose intolerance (GI) can be defined as dysglycemia that comprises both prediabetes and diabetes. "We have previously demonstrated that chronic icv apelin infusion triggered the onset of glucose homeostasis disorders, e.g., glucose intolerance and insulin resistance." (PMID 27549402, 2016). "For these reasons, in our studies BALB/c mice have proven more suitable than C57BL6/J mice to study apelin resistance, since C57BL6/J mice are known to display impaired glucose intolerance that could have complicated the readouts." (PMID 35406586, 2022).
Hepatic steatosis (5 papers, 2019 to 2025). Steatosis is a term used to denote lipid accumulation within hepatocytes. "Similarly in the same model chronic administration of [Pyr1]apelin-13 systemically over 28 days, exhibited anti-diabetic properties by directly targeting lipid metabolism thus reducing hepatic steatosis." (PMID 31472173, 2019). "Interestingly, in a study of obese mice, apelin treatment resulted in decreased hepatic steatosis by reducing de novo lipogenesis, although this may be an indirect effect due to the increase in insulin sensitivity." (PMID 39519480, 2024). "Finally, this study provides evidence that TM4SF5 expression in hepatocytes can promote abnormal food-intake behaviors such as increased eating during inappropriate mealtimes, which is supported by TM4SF5-mediated apelin expression, leading to initiation of hepatic steatosis toward NAFLD features." (PMID 37670786, 2023). "Animal models demonstrate that apelin and ML221 injections affect liver steatosis, inflammation, and fibrosis." (PMID 39744169, 2025).
pancreatic cancer (5 papers, 2021 to 2024). "Our study provides the first evidence of the involvement of the apelin signaling pathway in pancreatic cancer development through the upregulation of oncogenes and glycolysis-related gene expression, thus promoting tumor cell growth and migration." (PMID 36142542, 2022). "We then determined the apelin gene expression in pancreatic cancer cell lines in comparison with HUVECs, which are described to express apelin." (PMID 36142542, 2022). "Given the high frequency of apelin gene upregulation in human pancreatic cancer, we next determined the expression pattern of the apelin peptide and its receptor in human pancreas sections from 49 patients diagnosed with PDAC." (PMID 36142542, 2022). "Consistent with this important role of glucose metabolism in pancreatic cancer growth, we identified GLUT1 and HK2 as two of the metabolic genes upregulated by apelin that were previously implicated in PDAC." (PMID 36142542, 2022). "This overexpression of apelin peptides extends our previous results which were obtained at the mRNA level in human pancreatic cancer." (PMID 36142542, 2022). "Based on these data, we finally investigated the effect of apelin signaling inhibition on pancreatic tumor growth." (PMID 36142542, 2022). "Collectively, these findings provide new mechanistic insights into pancreatic tumor burden and establish apelin signaling as a novel and promising therapeutic target." (PMID 36142542, 2022). "In the current study, we demonstrate the involvement of apelin signaling in pancreatic tumor growth and our data unravel a new mechanism of action of apelin to promote tumor growth." (PMID 36142542, 2022). "Apelin signaling function in tumor cells was characterized in pancreatic tumor cell lines by Western blot as well as proliferation, migration assays and in murine orthotopic xenograft experiments." (PMID 36142542, 2022). "Our data clearly establish that the co-expression of apelin and APJ by pancreatic tumor cells fosters tumor growth, whereas loss of the apelin receptor dramatically reduces the tumor burden in murine orthotopic xenograft experiments." (PMID 36142542, 2022). "In this study, we identified the apelin signaling pathway as a new regulator of pancreatic tumor growth." (PMID 36142542, 2022). "Accordingly, further experiments will be necessary to more precisely define the mechanism involved in the upregulation of those oncogenes through apelin signaling in pancreatic tumor cells." (PMID 36142542, 2022). "Pancreatic tumor cell stimulation by apelin induces inhibitory phosphorylation of GSK-3, a direct downstream Akt effector, and positively regulates β-catenin, c-myc and cyclin D1 protein levels." (PMID 36142542, 2022). "On the contrary, inhibition of apelin signaling drastically reduced pancreatic tumor development." (PMID 36142542, 2022). "Likewise, this secreted insulin could positively regulate apelin expression in cancer cells (as described for adipocytes) and act concomitantly with insulin to promote the proliferation and migration of pancreatic cancer cells." (PMID 36142542, 2022). "Thus, MiaPaCa-2 cells represented the more suitable cell model to define more precisely the apelin signaling function in pancreatic cancer cells since apelin and APJ are co-expressed at the higher level in those cells as observed in human PDAC and mouse models of PDAC." (PMID 36142542, 2022). "Among all the different cancers studied by cancer profiling arrays, the extent of apelin upregulation observed in pancreatic cancer reached a 3.5-fold mean increase with the highest frequency (5/7), suggesting that apelin signaling could play an important role in this disease." (PMID 36142542, 2022). "Moderate labeling was observed for apelin and APJ at the different stages of pancreatic cancer as well as in PanINs." (PMID 36142542, 2022).
pancreatic cancer (continued). "To investigate the tumor cell function of the apelin signaling pathway, we first analyzed the endogenous expression of APJ and apelin in different human pancreatic cancer cell lines (MiaPaCa-2, Capan 1, Panc 1 and BxPC 3)." (PMID 36142542, 2022). "On the pancreatic tumor cell level, the internalization of APJ induced by apelin is the basis for activation of a PI3K/Akt/GSK-3 pathway." (PMID 36142542, 2022). "The top pathways suggested tRNA splicing, vitamin C transport, apelin liver signaling, metabolism of aryl hydrocarbon receptor (AHR) signaling, glycoprotein VI platelet (GP6) signaling, and SPINK1 pancreatic cancer pathway." (PMID 34685781, 2021). "With apelin and APJ being co-expressed by tumor cells both in human pancreatic cancer and PDAC mouse models, we next wondered whether endogenous apelin secreted by pancreatic tumor cells could promote the same effects." (PMID 36142542, 2022). "The top canonical pathways of Cluster 1 included pancreatic cancer initiation pathways, including SPINK1 Pancreatic Cancer Pathway48, and multiple normal pancreatic function related pathways, including FXR/RXR Activation49,50, Apelin Adipocyte Signaling Pathway51,52 and Retinol Biosynthesis53,54." (PMID 35941362, 2022). "In this context—β-arrestins 1 and 2 internalizing with APJ following apelin stimulation —those scaffold proteins could participate with apelin-induced p110α and γ activation to promote PI3K/Akt signaling and pancreatic tumor burden." (PMID 36142542, 2022). "Whereas the apelin secreted by HUVEC cells was quantifiable, we were not able to confirm apelin secretion in the culture medium of the pancreatic cancer cell lines, maybe due to the limit of sensitivity of the kit." (PMID 36142542, 2022).
periodontitis (5 papers, 2022 to 2026). An acute or chronic inflammatory process that affects the tissues that surround and support the teeth. "Elevated concentrations of certain apelin subforms in systemic diseases could therefore represent a pathomechanistic link for the association between periodontitis and certain systemic diseases." (PMID 39189510, 2024). "In addition, F. nucleatum caused downregulation of the expression of apelin and its receptor, suggesting a role of these molecules in the pathogenesis of periodontitis." (PMID 36902162, 2023). "We found that periodontitis patients had the highest GCF apelin levels, followed by gingivitis patients and healthy controls." (PMID 39189510, 2024). "In contrast, little is known about the role of the more recently described adipokine apelin in the etiopathogenesis of periodontitis and its link to metabolic diseases." (PMID 39409058, 2024). "In particular, clinical intervention studies are needed to further decipher the etiopathogenic role of apelin in periodontitis." (PMID 39189510, 2024). "The study showed that apelin concentrations were significantly higher in periodontitis patients than in the healthy control group." (PMID 39409058, 2024). "The study showed that apelin concentrations were significantly higher in the periodontitis group than in the healthy control group." (PMID 39189510, 2024). "In particular, clinical intervention studies are needed to further decipher the etiopathogenetic role of apelin subforms in periodontitis." (PMID 39189510, 2024). "The local production of apelin/APJ in PDL cells also suggests a role of these molecules in the pathogenesis of periodontitis." (PMID 36902162, 2023). "Clinical studies of experimental gingivitis and periodontitis as well as periodontal therapy, i.e., intervention, should further clarify the role of apelin locally in the periodontium but also systemically for the whole organism." (PMID 36902162, 2023). "The study showed that apelin levels were higher in the periodontitis group compared with the healthy control." (PMID 36902162, 2023). "Therefore, this study aimed to evaluate salivary apelin and asprosin levels in periodontally healthy individuals, patients with periodontitis, and patients with periodontitis + DM and to investigate their associations with clinical periodontal parameters." (PMID 41975764, 2026). "Our in vitro experiments therefore suggest that apelin may play a modulatory role in the pathogenesis of periodontitis." (PMID 39409058, 2024). "Again, the highest apelin concentrations were found in patients with periodontitis and T2DM." (PMID 39409058, 2024). "Recently, we have found that not only are systemic apelin concentrations altered in the context of periodontitis, but that different levels may also occur at the local level in the gingival sulcus." (PMID 39409058, 2024). "The aim of the present in vitro study was to further explore the pathomechanistic links between periodontitis and metabolic diseases by investigating possible effects of apelin on the actions of F. nucleatum with respect to wound closure, migration, proliferation and viability of PDL cells." (PMID 39409058, 2024). "Apelin could play a modulatory role in the pathogenesis of periodontitis, as it was able to compensate for the inhibitory effects of the periodontal pathogen F. nucleatum on PDL cell migration in vitro." (PMID 39409058, 2024). "Modulating the apelin-APJ system could lead to new immunomodulatory strategies in the treatment of periodontitis." (PMID 39189510, 2024). "Furthermore, apelin concentrations were highest in patients suffering from both periodontitis and T2DM suggesting that apelin plays a role in inflammation and glucose regulation." (PMID 39189510, 2024). "Finally, clinical studies in gingivitis and periodontitis patients should investigate the role of apelin in etiopathogenesis and therapy." (PMID 39409058, 2024).